CD70 (CD70 molecule)
Diseases named in the same sentence as CD70 in open-access papers (continued):
Sharing a sentence is not in itself a finding about the gene and the disease.
lung carcinoma (14 papers, 2015 to 2025). "In several tumour types, CD70 positivity was higher in metastatic specimens as compared to primary tissue biopsies, such as lung carcinoma (85.7%, N = 7 vs 40%, N = 80) (p = 0.048) and pancreatic carcinoma (87.5%, N = 8 vs 26.1%, N = 23) (p = 0.004)." (PMID 31652572, 2019). "As such, this combination regimen led to a significant decrease in lung cancer cell survival cell survival, broadening the applicability the applicability of CD70-targeting therapy." (PMID 29088768, 2017). "A total of 49 surgically resected lung cancer specimens were analyzed by immunohistochemistry (IHC) for CD70 expression." (PMID 25951351, 2015). "In conclusion, we are the first to demonstrate the immunotherapeutic potential of targeting CD70 in NSCLC with a maximum NK-cell mediated cytotoxicity of ARGX-110 in CD70 expressing lung cancer cell lines." (PMID 25951351, 2015). "Interestingly, CD70 expression was found to be even higher in metastatic specimens of lung carcinoma, pancreatic carcinoma and osteosarcoma, suggesting the importance of CD70 in progression of the disease." (PMID 34991665, 2022). "Interestingly, a recent study has shown that in the context of lung cancer, hypoxic conditions stimulated the synthesis of tumor vesicle proteins such as CD70, thereby possibly supporting immune suppression." (PMID 34991665, 2022). "Interestingly, we showed that the number of CD70 positive cells appeared to be even higher in metastatic tissue as compared to primary specimens in pancreatic carcinoma and lung carcinoma." (PMID 31652572, 2019). "In addition, IHC analysis suggested preferential expression of CD70 in T4 stage lung cancer (2 out of 5 T4NxMx biopsies (40%) with >10% CD70 positivity)." (PMID 25951351, 2015). "The antitumor efficacy of these T cells was further compared with WT control CAR-T cells or no cells into NSG mice bearing CD70-expressing human non–small cell lung cancer (NSCLC) tumors." (PMID 37788104, 2023). "We identified an induction of CD70 expression on lung cancer cells upon low doses of cisplatin, independent of oxygen levels." (PMID 29088768, 2017).
pancreatic cancer (14 papers, 2010 to 2024). "CD70, which is a cytokine belonging to the tumor necrosis factor ligand family, is also a prognostic marker for pancreatic cancer and a potential therapeutic target for pancreatic cancer." (PMID 38268915, 2023). "The mRNA expression levels of CSTF2, FAF2, KIF20B, AKR1A1, APOM, KRT6C, and CD70, which were included in the prognostic model, were detected in different types of pancreatic cancer cell lines." (PMID 38268915, 2023). "CD70 is expressed in approximately 25% of pancreatic cancers and its elevated expression is correlated with increased metastasis and poorer response to chemotherapy." (PMID 37880707, 2023). "Taken together, these in vitro studies showed that SGN-75 has the potential to kill ovarian and pancreatic cancer cell lines that express moderate to high levels of CD70." (PMID 20664585, 2010). "Interestingly, CD70 expression was found to be even higher in metastatic lung carcinoma, pancreatic carcinoma and osteosarcoma, suggesting the importance of CD70 in the progression of the disease." (PMID 37093350, 2023). "This is the first reported study of anti-CD70 ADC anti-tumour activity in pancreatic cancer." (PMID 20664585, 2010).
autoimmune disease (13 papers, 2017 to 2025). A disorder resulting from loss of function or tissue destruction of an organ or multiple organs, arising from humoral or cellular immune responses of the individual to their own tissue constituents. "So, CD70 hypomethylation could contribute to autoimmune diseases whereas hypermethylation would be rather associated with the development of malignancies, in particular breast cancers." (PMID 30687318, 2018). "Notably, the CD27/CD70 signaling pathway has been extensively linked to the promotion of autoimmune diseases, whereas CD52 has been associated with inflammation suppression, suggesting that DCs may exert a dual mode of action on T cells." (PMID 38596682, 2024). "DNA demethylation of the Tnfsf7 promotor gene has previously been suggested to upregulate CD70 on T cells in the context of autoimmune diseases." (PMID 34991665, 2022). "CD70 is merely expressed upon T cell activation, and thus blocking the C27-CD70 complex has been proposed as an appealing treatment target for autoimmune disorders." (PMID 35300124, 2022). "Surface expression of CD70 has been associated with a higher risk of cancer malignancy and aberrant T-cell activation in part due to CD70/CD27 interactions that can induce excessive infiltration of T cells and cause autoimmune disease." (PMID 35216458, 2022). "CD70 is present on antigen-presenting cells and was found to be involved in T-lymphocyte activation, as well as in pathophysiology of autoimmune diseases including lupus erythematosus and rheumatoid arthritis." (PMID 32183058, 2020). "In fact, CD70 is a B cell co-stimulatory molecule, whose overexpression may contribute to autoimmunity, as observed in other autoimmune diseases like lupus and Sjögren's syndrome." (PMID 30687318, 2018). "During the triggering phase of allergic contact dermatitis, there is an increase in the expression of CD70 and the Th17-specific transcription factor retinoid orphan receptor gamma T. Managing this phenomenon could ameliorate symptoms of other autoimmune diseases like psoriasis." (PMID 38596682, 2024). "Particularly, in a study it has been proposed a three gene-expression panel that included IL10, OAS2, and CD70 genes that, according to the authors, were able to differentiate SLE patients from control subjects and from patients with other autoimmune diseases." (PMID 36428917, 2022). "In particular, a previous study proposed a T cell gene expression panel including the OAS2, CD70, and IL10 genes as useful biomarkers for SLE discrimination from other autoimmune diseases and for the monitoring of disease activity." (PMID 36428917, 2022). "In conclusion, we propose that the LCV-infected B cell may play a role in autoimmune disease as an atypical APC, which is highlighted by enhanced expression of co-stimulatory markers such as CD70 and CD95L." (PMID 28243437, 2017).
leukemia (12 papers, 2010 to 2025). A malignant (clonal) hematologic disorder, involving hematopoietic stem cells and characterized by the presence of primitive or atypical myeloid or lymphoid cells in the bone marrow and the blood. "Future studies aiming to generate novel combinatorial CAR constructs, to increase CD70 expression density on leukemia cell surface, or to improve the persistence of CD70-CAR-T cells in vivo will be needed to optimize CAR T cell responses for AML." (PMID 36845088, 2023). "Increasing CD70 expression density on leukemia cell surface can improve the efficacy of CD70-CAR-T cell-therapy." (PMID 36845088, 2023). "The importance of CD70 in lymphocyte and leukemia cell activation has been investigated in earlier studies, while the expression and emerging roles (e.g. immune escape) of CD70 have also been reported in various solid tumors." (PMID 29721188, 2018). "Furthermore, we evaluated the potential anti-leukemia effects of this CD70-CAR-T cell construct." (PMID 36845088, 2023). "It inhibits tumors through multiple mechanisms, including Fc-mediated cytotoxicity with enhanced ADCC and inhibition of CD70/CD27 signaling, resulting in the killing of malignant cells such as leukemia blasts and stem cells." (PMID 36239354, 2022). "CD70, a member of the tumor necrosis factor (TNF) family, is transiently expressed on activated T and B cells under normal physiological conditions but is aberrantly overexpressed in various hematological malignancies, notably leukemias." (PMID 40227793, 2025). "CD70+ T-cell numbers remained higher on CD4+ subsets, and this is noteworthy given the importance of CD4+-mediated alloreactive responses as demonstrated by the tumor cell HLA class II downregulation leading to leukemia relapse." (PMID 39028952, 2024). "We found that in mice engrafted with AML cells, treatment with CD70-CAR-T cells resulted in a significant reduction in tumor burden and prolonged survival; however, CD70-CAR-T cells became undetectable on day 18 post-infusion and eventually, all mice died from leukemia progression." (PMID 36845088, 2023). "CD70 blockade might also be considered as a prophylactic measure to prevent the generation of aGVHD, although here, it will be important to determine that the graft-versus-leukemia effect is not substantially attenuated." (PMID 39028952, 2024). "CD70 heterogeneously expressed on AML primary cells, including leukemia blasts, leukemic progenitor, and stem cells, but not expressed on normal HSCs and majority of blood cells." (PMID 36845088, 2023). "However, despite promising results in vitro, such CAR-T cells do not completely eliminate leukemia cells in vivo, suggesting the need either to generate a combinatorial CAR construct or to increase CD70 expression on leukemic cells before CAR-T cell exposure." (PMID 38927401, 2024).
nasopharyngeal carcinoma (12 papers, 2010 to 2025). A carcinoma arising from the nasopharyngeal epithelium. "Nasopharyngeal carcinoma cells promote the development and suppressive activity of Tregs through the interaction of CD70 and CD27." (PMID 40270603, 2025). "CD70 on nasopharyngeal carcinoma cells binds to CD27 on naïve CD4+ T cells, driving differentiation to Tregs and their activation." (PMID 40270603, 2025). "CD70 blockade synergized with an anti-PD-1 antibody to further enhance the immunotherapy efficacy in nasopharyngeal carcinoma." (PMID 38302980, 2024). "This study also demonstrates that CD70 blockade can act synergistically with anti-PD-1 treatment to reinvigorate T-cell immunity against nasopharyngeal carcinoma." (PMID 37024479, 2023). "Our findings identify CD70+ nasopharyngeal carcinoma cells as a metabolic switch that enforces the lipid-driven development, functional specialization and homeostasis of Tregs, leading to immune evasion." (PMID 37024479, 2023). "In nasopharyngeal carcinoma (NPC), the transcription of CD70 was found to be activated by NFKB2 upon infection with Epstein–Barr virus." (PMID 40629902, 2025). "Signaling between CD70 and CD27 was identified as the only significant contact interaction between CD4+ naïve T cells, Tregs, and nasopharyngeal carcinoma (NPC) cells in the TME." (PMID 37828948, 2023).
Autoimmunity (11 papers, 2013 to 2024). The occurrence of an immune reaction against the organism's own cells or tissues. "Behçet's syndrome and alopecia areata were diagnosed in the proband, thereby providing a potential link between CD70 deficiency and a higher risk for autoimmunity." (PMID 33996677, 2021). "Several reports have implicated CD70/CD27 pathway in autoimmunity." (PMID 23450201, 2013). "In line with previous published data demonstrating that overexpression of CD70 by dendritic cells alone breaks peripheral tolerance and induces autoimmunity, the injection of a blocking antibody to CD70 prevented CTL priming by unsuppressed DCs." (PMID 34423375, 2022). "The high expression of CD70 can directly High CD70 expression can directly induce CD27+ lymphocyte over-infiltration, while CD27 and CD70 co-stimulation of the pathway can impede Th17 effector cell differentiation and associated autoimmunity." (PMID 38596682, 2024). "Due to the therapeutic potential of Treg cell therapy in transplantation and autoimmunity, both disorders in which there is persistent antigen presence, future work is needed to determine the role of CD70+ Tregs in vivo in both steady state and inflammatory states." (PMID 32665635, 2020). "The CD27 and CD70 costimulatory pathway has been found to inhibit the transcription of the key effector molecules IL-17 and the chemokine receptor CCR6, subsequently attenuates associated autoimmunity, Cancer cells can reprogramme their metabolism to support cell growth and proliferation." (PMID 37732314, 2023). "A recent study also demonstrated that CD70/CD27 pathway impedes the differentiation of Th17 effector cells and attenuates accompanying autoimmunity in a mouse model of multiple sclerosis." (PMID 23450201, 2013). "In addition, DNAdemethylation of a particular gene, Tnfsf7 (CD70), has beenobserved in 16-wk autoimmune MRL-lpr mice compared with 5-wk miceprior to onset of autoimmunity." (PMID 33097564, 2020). "Interestingly, it was proposed that CD70 signaling generated by unaroused, premature APCs can inevitably lead to a lack of tolerance and autoimmunity development." (PMID 35300124, 2022).
myeloma (11 papers, 2019 to 2026). "We show in two cohorts of patients with multiple myeloma that CD70 is elevated in several high-risk disease categories and correlates with poor survival." (PMID 41144785, 2026). "This proliferative advantage results in elevated CD70 expression in advanced MM stages, particularly in extramedullary myeloma." (PMID 41872502, 2026). "CAR27/IL-15 NK cells exerted potent in vitro and in vivo cytotoxicity against CD70+ multiple myeloma cells, comparable with CAR27/IL-15 T cells, and remained effective in BCMA knockout models." (PMID 41144785, 2026). "In this study, we identified CD70-expressing myeloma cells as critical drivers of disease progression and propagation." (PMID 41872502, 2026). "We also investigated the validity of our results in a multiple myeloma mouse model of MM1S treated with anti-CD70-CAR/IL-15 (CAR70/IL-15) NK cells." (PMID 38238616, 2024). "Up-regulating the expression of costimulatory molecules such as CD40, CD80/86, 4-1BBL, OX40L, CD70 and B7RP on the surface of myeloma cells can increase the susceptibility of myeloma cells to attack by immune effector cells." (PMID 37275861, 2023). "CD70 is extensively expressed in Hodgkin and non-Hodgkin lymphomas, chronic lymphocytic leukemia, and multiple myeloma." (PMID 37849799, 2023). "The low and variable expression of CD70 on myeloma cells limits the use of CD70-directed CAR-T cells in MM." (PMID 31379824, 2019). "Furthermore, the ADCC-enhanced anti-CD70 antibody, cusatuzumab, demonstrated high efficacy in treating myeloma in xenotransplantation models." (PMID 41872502, 2026). "Moreover, we demonstrate the feasibility of targeting CD70 in myeloma using NK cells engineered with a chimeric antigen receptor (CAR) incorporating the CD70 cognate receptor CD27 and IL-15 (CAR27/IL-15)." (PMID 41144785, 2026). "CD70 is highly expressed in many cancers, including multiple myeloma." (PMID 41144785, 2026). "Preclinical trials have confirmed the high cytotoxic activity of CD70-specific CAR T cells with respect to myeloma cells, whereby the low toxicity of normal tissues has been noted, including hematopoietic stem cells, thanks to minimal CD70 expression of extratumor or activated immune cells." (PMID 40649828, 2025). "Hence, CD70 is a highly specific and biologically substantiated target for cellular therapy in multiple myeloma." (PMID 40649828, 2025). "CD70-specific CAR-NK cells demonstrated potent cytolytic activity against CD70+ MM cell lines, while showing the same cytotoxicity toward the CD70− H929 myeloma line as non-engineered NK cells, confirming their antigen specificity." (PMID 41303706, 2025). "CD70-targeting CAR NK cells exhibit potent cytotoxicity against CD70+ multiple myeloma cells and significantly improve survival in xenograft mouse models of multiple myeloma, even in the absence of BCMA expression." (PMID 41144785, 2026).
rheumatoid arthritis (10 papers, 2017 to 2025). A chronic, systemic autoimmune disorder characterized by inflammation in the synovial membranes and articular surfaces. "This study aimed to examine the role of CD70, which is highly expressed on fibroblast-like synoviocytes (FLS), in rheumatoid arthritis (RA) patients." (PMID 35216458, 2022).
T cell lymphomas (10 papers, 2022 to 2025). "On the contrary, only CD70 expression is observed on chronic active Epstein-Barr virus associated T cell lymphoma (a rare complication of latent Epstein-Barr virus infection) and T cell acute lymphoblastic leukemia." (PMID 34991665, 2022). "These CD70 CAR-NK cells were able to eradicate T cell lymphoma cells both in vitro and in mouse xenograft models using the MT4 ATLL cell line and represent a promising novel approach." (PMID 41295262, 2025). "Further, ADP-520 demonstrated robust cytotoxicity and cytokine production against additional CD70-expressing cell lines, including the MJ and HuT78 T-cell lymphoma cell lines, and the non-small cell lung cancer (NSCLC) line, NCI-H1975." (PMID 40519930, 2025). "Allogeneic CTX130 CAR T cells avoid fratricide by CRISPR-mediated CD70 knockout and have demonstrated a promising objective response rate in patients with heavily pre-treated T-cell lymphoma during a Phase 1 clinical study." (PMID 40519930, 2025). "CD70’s direct pathophysiological role coupled with its overexpression in T cell lymphomas make it a promising candidate for targeting." (PMID 41295262, 2025). "In this first-in-human phase I trial of allogeneic CD70-targeting CAR-T cells for relapsed/refractory T cell lymphoma, 18 of 39 patients achieved an objective response, including 10 with PTCLs (4 CRs and 6 PRs)." (PMID 41295262, 2025). "In the Phase I COBAL-LYM dose escalation study of allogeneic CD70-CAR T-cells (CTX 130) for R/R mature T-cell lymphomas, among four patients with PTCL treated at the dose level of 3–4 the ORR was 75%." (PMID 39456582, 2024). "Cellular therapies are at the outset in T-cell lymphomas, but the first large report of an allogeneic CD70 CAR T-cell therapy hints at promise in this modality." (PMID 36765544, 2023). "CD70 is aberrantly overexpressed across several T cell lymphoma subtypes, notably in cutaneous T cell lymphoma (CTCL), including MF and primary cutaneous ALCL, and in certain PTCL subtypes, such as PTCL-NOS, systemic ALK-negative ALCL, nTFHL-AI, and acute-type ATLL." (PMID 41295262, 2025). "Interestingly, binding of sCD27 to CD70 was shown to induce proliferation on extranodal NK/T cell lymphomas." (PMID 34991665, 2022). "A phase I trial of CTX130, an allogeneic CD70-directed CAR-T therapy, demonstrated a 46.2% ORR in relapsed or refractory T-cell lymphoma, highlighting its translational potential in CD70-positive tumors." (PMID 41154432, 2025). "Other ADCs and related targeted therapies under investigation for T-cell lymphomas include those targeting CD3, CD70, CD38, and TRBC1." (PMID 39456582, 2024). "Upon transfection with CD70, IMM40H bound to the CD70-negative cell line CHO (Chinese Hamster Ovary) and Jurkat (T cell lymphoma cell line), proving its specificity for CD70." (PMID 37849799, 2023).
diffuse large B-cell lymphoma (9 papers, 2017 to 2025). "In line with these notions, somatic mutations and deletions affecting both alleles of CD70 have been observed in diffuse large B-cell lymphomas (DLBCLs), supporting its potential role as a tumor suppressor." (PMID 33996677, 2021). "However, the impact of intratumoral CD70 on the initiation, progression, and immune response in diffuse large B-cell lymphoma (DLBCL) remains poorly understood." (PMID 39446784, 2024).